SPAG6 (sperm associated antigen 6)
Diseases named in the same sentence as SPAG6 in open-access papers (continued):
Sharing a sentence is not in itself a finding about the gene and the disease.
osteosarcoma (2 papers, 2022 to 2024). A usually aggressive malignant bone-forming mesenchymal neoplasm, predominantly affecting adolescents and young adults. "Moreover, SPAG6 may also be associated with metastasis, the Enneking stage, and the pathological grade of osteosarcoma." (PMID 39508041, 2024). "In this study, we detected the association between SPAG6 and NM23 and the clinicopathological parameters of metastasis and prognosis of osteosarcoma using immunohistochemical staining, qRT-PCR, and Western blotting methods." (PMID 36199573, 2022). "In the present study, we reported that SPAG6 was upregulated more in osteosarcoma tissues than the controls in mRNA and protein levels." (PMID 36199573, 2022). "Until now, there are few reports about the association of the expression of SPAG6 and NM23 with the metastasis and prognosis of osteosarcoma, and the precise role of SPAG6 is unclear." (PMID 36199573, 2022). "The overall survival rate of osteosarcoma patients with SPAG6 positive expression was significantly lower than that with SPAG6 negative expression." (PMID 36199573, 2022). "The positive expression rate of SPAG6 protein was 71.43% (30/42) in 42 cases of osteosarcoma tissues and 33.33% (4/12) in 12 cases of osteochondroma tissues, with p < 0.05 for all." (PMID 36199573, 2022). "Furthermore, research showed that the expression of SPAG6 was positively related to the pathological grade, distant metastasis, Enneking stage, and worst prognosis of patients with osteosarcoma." (PMID 36199573, 2022). "The staining of SPAG6 was located in the cytoplasm and nucleus of osteosarcoma and control tissues." (PMID 36199573, 2022). "However, our study only detected mRNA and proteins in human osteosarcoma tissues; the molecular mechanism of SPAG6 regulating NM23 will be studied in our future research." (PMID 36199573, 2022). "We found that mRNA and protein levels of SPAG6 were significantly higher than those of the adjacent normal tissues, while the expression of NM23 was lower in osteosarcoma tissues than in controls." (PMID 36199573, 2022). "So far, there are no reports about the clinical significance and correlation between SPAG6 expression and NM23 in osteosarcoma." (PMID 36199573, 2022). "This suggested that SPAG6 and NM23 should be considered candidate prognostic biomarkers for patients with osteosarcoma." (PMID 36199573, 2022). "The expression of SPAG6 and NM23, distant metastasis, pathological grade, and Enneking stages were found to be independent prognostic factors of osteosarcoma using the Cox multivariate analysis method (p < 0.05 for all)." (PMID 36199573, 2022). "The results of the Western blot analysis indicated that the relative intensity of SPAG6 and NM23 protein blots was 1.80- and 0.78-fold greater in osteosarcoma tissues than in control tissues, with p < 0.05 for all." (PMID 36199573, 2022). "In thirty cases of the SPAG6 positive expression group, there were only six cases of NM23 positive expression in human osteosarcoma tissues." (PMID 36199573, 2022). "The mRNA and protein levels of SPAG6 were significantly higher than those of the adjacent normal tissues, while the expression of NM23 was lower in osteosarcoma tissues than that in the controls (p < 0.05 for all)." (PMID 36199573, 2022). "We deduced that SPAG6 may promote distant metastasis by suppressing NM23 and lead to worse prognosis in osteosarcoma." (PMID 36199573, 2022). "The expression of SPAG6 protein was positive while that of NM23 was negative, associated with distant metastasis, pathological grade, and Enneking stage of osteosarcoma patients, with p < 0.05 for all." (PMID 36199573, 2022). "The Kaplan−Meier curve analysis (log-rank test) results showed that the overall survival rate of osteosarcoma patients with SPAG6 positive expression was significantly less than that with SPAG6 negative expression, while the rate was adverse in NM23 expression with p < 0.05 for all." (PMID 36199573, 2022).
osteosarcoma (continued). "But in the twelve cases of the SPAG6 negative expression group, there were nine cases of NM23 positive expression in human osteosarcoma tissues." (PMID 36199573, 2022).
adenovirus infection (1 paper, 2015). "In contrast, the acetylated tubulin expression level was dramatically reduced in the Spag6-deficient MEFs, and the reduced acetylated tubulin expression was rescued by forced-expression of SPAG6 using adenovirus infection." (PMID 26585507, 2015).
asthma (1 paper, 2020). "Among ten hub DEGs identified for the asthma-COPD, nine DEGs including SPAG6, C7orf57, SYTL3, LRRC48, TEKT3, CCDC146, CETN2, CCDC19, and C14orf45 were identified as the novel genes." (PMID 31952466, 2020).
benign breast disease (1 paper, 2019). "Since plasma shows lower cfDNA concentrations compared to serum, we tested the methylation frequency of SPAG6, PER1, NKX2-6 and ITIH5 in a plasma cohort, consisting of women with a benign breast disease (n = 14) and invasive breast cancer (n = 111)." (PMID 31741713, 2019).
ciliopathies (1 paper, 2025). "The study found that SPAG6, TRAF3IP1, IFT22, and KIF3B showed lower correlations with ciliopathies, while IFT172, TTC21B, CEP290, ACTB, and DYNC1H1 were highly correlated." (PMID 40432967, 2025).
cryptorchidism (1 paper, 2023). The failure of one or both testes of a male fetus to descend from the abdomen into the scrotum during the late part of pregnancy. "According to the extent of difference between cryptorchidism and normal testis, the expression of seven downregulated genes (PLCZ1, AKAP4, AKAP3, IZUMO1, SPAG6, CAPZA3, and ROPN1L) were further selected for validation by qPCR." (PMID 38027210, 2023).
infertility disorder (1 paper, 2016). Inability to conceive for at least one year after trying and having unprotected sex. "This novel report demonstrates the requirement of SPAG6 for optimal synapse formation and function, its direct role in immune cell function, and provides a novel mechanism for infertility disorders related to SPAG6." (PMID 27169488, 2016).
invasive breast carcinoma (1 paper, 2019). A carcinoma that infiltrates the breast parenchyma. "SPAG6 shows, at a cut-off methylation of 8.5% and specificity of 82.3%, an equal sensitivity for DCIS- (44%) and early invasive breast cancer (39%) detection." (PMID 31741713, 2019). "We initially assessed promoter methylation of SPAG6, PER1, NKX2-6 and ITIH5 in a serum cohort consisting of samples of women with benign disease (n = 34), DCIS (n = 27) and early invasive breast cancer (n = 42)." (PMID 31741713, 2019).
Multiple Myeloma (1 paper, 2025). "Thus, this study aims to further explore SPAG6’s role in multiple myeloma and clarify the underlying mechanisms." (PMID 40535772, 2025). "The expression level of SPAG6 protein in the bone marrow of multiple myeloma (MM) patients was observed to be elevated compared to that of the control group." (PMID 40535772, 2025). "To comprehend the function of SPAG6 in multiple myeloma (MM) patients, we examined the correlation between the relative expression levels of SPAG6 mRNA and the clinical features of MM patients." (PMID 40535772, 2025). "This study demonstrated SPAG6 upregulation in plasmacytoma tissues, and the IRS score in patients with multiple myeloma was significantly higher compared to those with solitary bone plasmacytoma." (PMID 40535772, 2025).
otitis (1 paper, 2015). "Mutations leading to ciliary defects (such as those seen in the Chibby- and Spag6-knockout mice) also predispose to otitis, owing to reduced mucociliary clearance in these regions." (PMID 25765466, 2015).
plasma cell tumors (1 paper, 2025). "The findings suggested that if SPAG6 influences the function of plasma cell tumors, this molecule might play a role in promoting their development." (PMID 40535772, 2025).
plasmacytoma (1 paper, 2025). Plasmacytoma is a localized mass of neoplastic monoclonal plasma cells that represents approximately 5% of all plasma cell neoplasms. "This suggests that SPAG6 expression may influence the phenotype of plasmacytoma and is associated with the progression of plasma cell disease." (PMID 40535772, 2025).
pneumonia (1 paper, 2013). An acute, acute and chronic, or chronic inflammation focally or diffusely affecting the lung parenchyma, caused by an infection in one or both of the lungs (by bacteria, viruses, fungi, or mycoplasma.). "Mice lacking both sperm associated antigens 6 (Spag6) and 16 L (Spag16L), which have been shown to interact in the cilium, have severe lower airway disease characterized by pneumonia, atelectases, and hemorrhage." (PMID 24360193, 2013).
virus infection (1 paper, 2015). "Even though the abnormal morphology and reduced acetylated tubulin levels were rescued by re-expression of SPAG6 using an adenovirus vector, almost all the cells died three to four days after virus infection." (PMID 26585507, 2015).
tumor (19 papers, 2014 to 2026). "The genes L1TD1 (LINE-1 Type Transposase Domain Containing 1) and SPAG6 (Sperm Associated Antigen 6) are tumor-specifically methylated in NSCLC." (PMID 32299382, 2020). "The differential expression of SPAG6 in tumor tissues indicates its diagnostic potential." (PMID 31660426, 2019). "SPAG6 was positively expressed in MM cell lines, plasma cell tumor tissue specimens, and MM patient bone marrow samples." (PMID 40535772, 2025). "In comparison with the control group, the tumor volume and weight increased in the SPAG6 overexpression group but decreased in the SPAG6 knockdown group, indicating that SPAG6 facilitated tumor growth in vivo." (PMID 39508041, 2024). "In our study, the upregulation of SPAG6 was found to facilitate cell proliferation and tumor growth." (PMID 39508041, 2024). "SPAG6 was also reported that can regulate tumor cell proliferation, apoptosis, invasion, and metastasis." (PMID 36006904, 2022). "In NOD/SCID mice, the tumor volume of the decitabine group was significantly smaller than that of the placebo group, and the tumor volume of the SPAG6 silencing combined with the decitabine treatment group was the smallest." (PMID 35045671, 2021). "The upregulated genes CPLX3 and SPAG6 appeared to be associated with poor survival, whereas the downregulated genes GDPD5, NXPH1, and AHI1 were identified as tumor suppressors." (PMID 34950701, 2021). "Studies have increasingly shown a critical role of SPAG6 in tumor progression, especially in hematological malignancies that harbor higher SPAG6 levels compared with solid tumors." (PMID 31660426, 2019). "New evidence shows that SPAG6 gene regulates tumor cell proliferation, apoptosis, invasion, and metastasis." (PMID 31660426, 2019). "Our results demonstrate that tumor-specific methylation of SPAG6 and L1TD1 is a frequently occurring event in NSCLCs and they suggest that methylation plays an important role in the transcriptional regulation of these genes." (PMID 28093071, 2017). "Frequent tumor-specific DNA methylation of SPAG6 and L1TD1 was detected when we analysed TU and corresponding NL samples of NSCLC patients." (PMID 28093071, 2017). "All these tumor cell lines were found to be SPAG6 and L1TD1 methylated with percentages of methylation ranging between 71% (SK-OV3 cells) and 98% (FaDu cells) for SPAG6 methylation and between 88% (BxPC-3 cells) and 100% (FaDu cells) for L1TD1 methylation." (PMID 28093071, 2017). "IHC was used to determine the expression of GSTP1 and SPAG6 in tumor tissues." (PMID 39508041, 2024). "In vivo, the subcutaneous tumorigenesis experiment we conducted provides insights into the role of SPAG6 in tumor growth in mice to a certain extent; however, the mechanism through which SPAG6 regulates the progression of AML in this model requires further experimental investigation." (PMID 39508041, 2024). "In vivo, SPAG6 could also promote tumor growth, suggesting that SPAG6 may serve as a pro-tumor factor." (PMID 39508041, 2024). "Our results suggest that SPAG6 may provide a potential tumor marker and a promising antitumor therapeutic target." (PMID 36199573, 2022). "However, whether SPAG6 functions as an oncogene or a tumor suppressor gene remains undetermined." (PMID 40535772, 2025). "In the in vivo experiments, a xenografted tumor model was constructed, and the expression of SPAG6 and GSTP1 in tumor tissues was detected by IHC." (PMID 39508041, 2024). "To verify the effect of SPAG6 on tumor growth in vivo, we selected HL60 and THP-1 cells for subcutaneous tumor formation experiments." (PMID 39508041, 2024). "The downregulated genes GDPD5, NXPH1, and AHI1 were identified as tumor suppressors, while the upregulated genes CPLX3 and SPAG6 were regarded as oncogenes." (PMID 34950701, 2021). "Overall, our results demonstrate that SPAG6 and L1TD1 are tumor-specifically methylated in NSCLCs and that DNA methylation is involved in the transcriptional regulation of these genes." (PMID 28093071, 2017).
tumor (continued). "Taken together we identified methylation as a potential mechanism for frequent downregulation of SPAG6 and L1TD1 in NSCLCs and suggest a putative role of L1TD1 in tumor cell development." (PMID 28093071, 2017). "Two of them, SPAG6 and L1TD1, were selected for detailed investigation of gene expression, gene-specific methylation and potential tumor-cell growth suppressing properties in NSCLCs." (PMID 28093071, 2017). "Differences in SPAG6 and L1TD1 methylation between TU and NL samples were statistically significant (p < 0.0001, respectively) demonstrating that both genes are tumor-specifically methylated." (PMID 28093071, 2017). "Mechanistically, SPAG6 promoted the translocation of MYO1D from the cytoplasm to the cell membrane, thereby activating the PI3K/AKT and ERK signaling pathways, which ultimately accelerating AML cell proliferation and tumor progression." (PMID 39508041, 2024). "For NKX6-2, SPAG6, ZIC1 and ZNF154, methylation frequencies in recurrence and progression tumours were marginally greater than their no-recurrence counterparts, and were overall broadly similar to the frequencies apparent in low/intermediate-grade tumours." (PMID 26332997, 2015). "Overall, these data suggest that deregulated expression of SPAG6 and L1TD1 may play a role not only in the pathogenesis of NSCLCs but also in tumors of other entities and that expression of these 2 genes differs between certain tumor types." (PMID 28093071, 2017). "Since SPAG6 and L1TD1 were found to be frequently methylated and downregulated in NSCLC cells and are located in chromosomal regions where frequent LOH was observed, we hypothesized that these genes may have tumor-cell growth suppressing properties." (PMID 28093071, 2017). "We observed frequent downregulation of SPAG6 and L1TD1 mRNA expression in primary tumor ﻿(TU) samples compared to corresponding non-malignant lung tissue (NL) samples of NSCLC patients." (PMID 28093071, 2017). "The mean methylation level increase from no-recurrence to recurrence and progression tumours was not significant for NKX6-2, SPAG6, ZIC1 and ZNF154." (PMID 26332997, 2015).
cancer (11 papers, 2015 to 2024). A tumor composed of atypical neoplastic, often pleomorphic cells that invade other tissues. "Sperm-associated antigen 6 (SPAG6) has been implicated in the onset and progression of various human cancers, with its expression levels significantly elevated in AML." (PMID 39508041, 2024). "We next tested the response of both immortalized (left) and passage two (right) wild-type and Spag6-deficient MEFs to paclitaxel, a microtubule stabilizer, and a compound widely used for cancer therapy." (PMID 26585507, 2015). "A variety of human cancers have been shown to be associated with SPAG6." (PMID 34950701, 2021). "The fact that the Spag6-deficient MEFs are more sensitive to paclitaxel suggests that reducing SPAG6 expression in paclitaxel-insensitive cancers might be an effective therapeutic approach." (PMID 26585507, 2015). "SPAG6 acts a crucial role in immuno-regulation, and participate in the occurrence and progression of human cancers." (PMID 36006904, 2022). "Studies also show a positive correlation between gluten-tubulin and SPAG6 overexpression in malignant tumors." (PMID 31660426, 2019). "Tissue-specific knockout or transgenic mouse models can greatly elucidate the role of SPAG6 in cancer development." (PMID 31660426, 2019). "Some studies found that SPAG6 is also a promising anti-cancer therapeutic candidate." (PMID 36199573, 2022). "In addition, studies have shown that SPAG6 expression is significantly increased in a number of cancers, which further supports the notion that mammalian SPAG6 performs other functions in addition to modulating cilia/flagella motility." (PMID 35159146, 2022). "Furthermore, SPAG6 is also a promising anti-cancer therapeutic target because its absence can stabilize the microtubules, enhance the effects of apoptosis-inducing drugs, and induce cell-cycle arrest." (PMID 31660426, 2019). "Taken together, targeting SPAG6 could be a novel strategy for the treatment of human diseases including cancer." (PMID 31660426, 2019). "Notably, SPAG6 has been demonstrated to participate in the occurrence and progression of a variety of human cancers." (PMID 31660426, 2019). "Therefore, in this review, we describe the physiological function and mechanism of SPAG6 in human normal cells and cancer cells." (PMID 31660426, 2019). "It has also been speculated that overexpression of SPAG6 might be the reason why some cancers are resistant to microtubule-targeting drugs, such as paclitaxel." (PMID 28819108, 2017). "We speculate that overexpression of SPAG6 might be the reason why some cancers are resistant to microtubule-targeting drugs, such as paclitaxel." (PMID 26585507, 2015). "Given the fact that SPAG6 is also up-regulated in cancers, high SPAG6 expression in these cancer cells may also increase Glu-tubulin expression." (PMID 26585507, 2015). "We also highlight that SPAG6 gene may be an effective biomarker for the diagnosis of human cancer." (PMID 31660426, 2019). "Sperm-associated antigen 6 (SPAG6) gene, first identified in human testicular tissue, also named CT141 and pf16, is considered a cancer-testis antigen (CTA) and involved in many cancers." (PMID 36199573, 2022). "There is increasing evidence that the expression of CTAs might be involved in tumorigenesis, however, so far there are no reports available about an involvement of SPAG6 in malignant disease biology or cancer cell invasiveness." (PMID 28093071, 2017).
hematological malignancies (4 papers, 2019 to 2025). "Sperm - associated antigen 6 (SPAG6), a member of the cancer/testis antigen (CTA) family, has been linked to multiple hematologic malignancies." (PMID 40535772, 2025). "Therefore, SPAG6 is a potential prognostic factor in hematological malignancies." (PMID 31660426, 2019).
SPAG6 also shares sentences with these, for which no sentence is quoted: infection (4 papers); bladder cancer (2); otitis media (2); ovarian carcinoma (2); abortion (1); acute lymphoblastic leukemia (1); adenocarcinoma (1); Breast Tumours (1); Cirrhosis (1); colon cancer (1); colorectal carcinoma (1); cone-rod dystrophies (1); gastric cancer (1); genetic disease (1); head and neck carcinoma (1); hepatocellular carcinoma (1); kidney clear cell carcinomas (1); lung adenocarcinoma (1); lung disease (1); malaria (1); melanoma (1); myeloid leukemia (1); Osteochondroma (1); pancreatic cancer (1); renal cell carcinoma (1); squamous cell carcinoma (1); T-cell leukemia (1); testicular germ cell tumor (1).